CXCL14 (C-X-C motif chemokine ligand 14)
Diseases named in the same sentence as CXCL14 in open-access papers (continued):
Sharing a sentence is not in itself a finding about the gene and the disease.
tumor (continued). "Previous studies have shown that CXCL14 interferes with IL-8 and CXCL12 signaling, which are important for tumor cell migration and invasion." (PMID 27143385, 2016). "Further, Cxcl14 reexpression significantly increases natural killer (NK), CD4+ T, and CD8+ T cell infiltration into the tumor-draining lymph nodes in vivo." (PMID 27143385, 2016). "Reexpression of Cxcl14 increases natural killer, CD4+ T, and CD8+ T cells in tumor-draining lymph nodes in vivo." (PMID 27143385, 2016). "During our analysis the most prominent differences connected with the location of the tumor were noted for the IRX2, PAX3, CXCL14, LHX2, SIX6, CNTN1 and SIX1 genes." (PMID 26497896, 2015). "Thus, CD4+ T cells may also mediate upregulated expression of angiostatic chemokines such as CXCL9, CXCL10, and CXCL14 that are capable of inhibiting tumor growth or may downregulate expression of the chemokine receptor CXCR2 or its many ligands that promote angiogenesis." (PMID 26618181, 2015). "To further confirm the correlation, we detected the expression of CXCL14 and S100A6 in the subcutaneous xenograft tumor tissues by immunohistochemical analysis." (PMID 25760073, 2015). "Thus, we believe that our CXCL14 Tg mouse model may be useful for investigation of the molecular mechanisms involved in multi-step tumour progression and suppression and that further research concerning the clinical application of CXCL14 to treat cancer is warranted." (PMID 25765541, 2015). "Cxcl14, a CXCR4-inhibitory ligand, localized to the outer tumor margins, whereas Cxcl16, a CXCR6 ligand important for effector T cells and ILC2s, was enriched in the tumor core." (PMID 40630529, 2025). "The knockdown of CXCL14 in OSCC lines (MOC1 and MOC2) injected into immunocompetent mice slows tumor growth in a TIL-dependent fashion, suggesting that CXCL14 may have a protective role." (PMID 40724900, 2025). "The upregulation of miR-181b-5p and its negative correlation with CXCL14 expressions suggest a potential role in the post-transcriptional suppression of tumor-suppressive pathways." (PMID 40565366, 2025). "Meanwhile, C-X-C motif chemokine ligand 14 (CXCL14)-positive CAFs contribute to cancer progression by enhancing epithelial–mesenchymal transition (EMT) and promoting angiogenesis, thereby facilitating increased tumor invasiveness and vascularization." (PMID 40940809, 2025). "Interestingly, restoration of CXCL14 enhances antigen presentation by increasing MHC-I and T-cell infiltration into tumors, resulting in tumor suppression in vivo." (PMID 38911052, 2024). "Moreover, ChIP analysis of tumor tissues revealed that the recruitment of BACH1 to the promoters of CEMIP, CXCL14, and NGFR was markedly enhanced in tumors from the Keto diet group compared to the Ctrl group." (PMID 38838145, 2024). "Both the RNA and protein abundance of CXCL14 was significantly elevated in tumor tissues compared to normal adjacent tissues." (PMID 39358777, 2024). "Moreover, researchers also found that the upregulation of CXCL14 facilitated OC-related tumor cell proliferation through STAT3 signaling pathway, while promoted epithelial-mesenchymal transition and tumor metastasis through Wnt/β-catenin pathway." (PMID 37393391, 2023). "Interestingly, although ganciclovir ablated Cxcl14 expression and TAM infiltration, tumor metastasis was increased." (PMID 35439170, 2022). "The role of CXCL14 in regulating tumor metastasis is not elucidated, and further investigation is warranted in the expanding field of chemokine research in TME." (PMID 35439170, 2022). "Our work shows that CXCL14 promotes TAM recruitment and polarization, promoting tumor metastasis." (PMID 35439170, 2022). "TIDE (Tumor Immune Dysfunction and Exclusion) analysis, which estimates the cytotoxic T lymphocyte level (CTL score) in tumor samples, also demonstrated a positive correlation between CXCL14 expression and CTL score in TNBC." (PMID 36012586, 2022).
tumor (continued). "CXCL14 expression in tumor tissues was not significantly correlated with histological type, age, sex or pathological stage." (PMID 35769715, 2022). "When all tumor samples analyzed without stratifying subtypes, CXCL14 expression showed negative correlation with infiltration of myeloid derived suppressive cell (MDSC), CD4+ Th1 and CD4+ Th2 cells." (PMID 36012586, 2022). "Since CCL20 showed the most prominent Ras-dependent upregulation among all tested chemokines, and previous findings supported a role for CXCL14 and CCL27 in tumour-immune surveillance, we decided to investigate further the role of CCL20 within the tumour microenvironment." (PMID 32601464, 2020). "Of interest, both chemokines were shown to activate fibroblasts, suggesting that CXCL14 and CXCL12 may co-operate in controlling fibroblast functions in various scenarios, including tissue repair, fibrosis and tumor progression." (PMID 33123134, 2020). "Analysis of CXCL14 at the mRNA and protein levels revealed its increased expression in primary tumor tissue compared to normal colon tissues but not in four of five CC tumor cell lines." (PMID 31752131, 2019). "Notably, HPK1 KD mice showed markedly increased pro-inflammatory pathways in response to priming with tumor antigens as shown by the enhanced related gene expression, e.g. S100A8, GZMB, NKp44, CXCL14, CX3CL1, CD1d2, KLRG1, CD11c, NLRP3 and MUC1." (PMID 30913212, 2019). "Some of these genes are of particular interest in the context of HCC: female-biased CXCL14 and ATF5 may modulate antitumor immune responses and have a tumor suppressor role in HCC." (PMID 31615477, 2019). "Many suppressors of individual processes have been reported; however, no reports have described molecules other than CXCL14 that suppress all the tumor progression steps." (PMID 31014014, 2019). "To determine whether CXCL14 suppresses HPV-positive tumor growth in vivo, we established ~20 clones of MOE/E6E7 cells reexpressing various levels of murine Cxcl14 using lentiviral transduction." (PMID 27143385, 2016). "Many independent studies have reported that CXCL14 was highly expressed in normal tissues, especially in normal kidney tissues, but absent in the tumor cell lines and primary tumors." (PMID 25760073, 2015). "We next randomly selected 8 genes aberrantly expressed in HCCs that had aberrant DNA methylation (CR1, ESR1, PTPN13, and SOCS2) or SCNA (C8A, CXCL14, ITGA6 and MARCO) to validate the array-based results in an independent sample set consisting 47 HCCs and paired non-tumor specimens." (PMID 25965583, 2015). "CXCL14 expression was significantly up-regulated in tumor tissues compared with adjacent nontumorous mucosa tissues (P < 0.001)." (PMID 23294544, 2013). "CXCL14, a novel non-ELR chemokine with yet uncharacterised receptor, has been reported to be associated with tumor progression and metastasis." (PMID 23294544, 2013). "As a unique member of the chemokine family, the receptor for CXCL14 has not yet been identified and the role of this molecule in tumor progression is controversial." (PMID 23294544, 2013). "This tumor-suppressing effect of the drug is not observed in the case of CXCL14/BRAK nonexpressing YCU-H891 cells." (PMID 23762619, 2012). "The precise molecular mechanisms of the tumor suppression are not clear at present; our data suggest CXCL14/BRAK is a multifunctional tumor suppressor." (PMID 23762619, 2012). "Whereas CXCL14 suppresses tumor growth, AIF1 seems to promote tumor cell proliferation." (PMID 21188144, 2010). "Given the extensive involvement of metabolic and signal transduction pathways in tumor cells, we aimed to identify the key components of T24 cells responsible for CAF activation and to determine whether the CXCL14/CCR7/STAT3/ERCC4 signaling axis is involved in this process." (PMID 40898244, 2025).
tumor (continued). "Notably, we identified a transitional myCAFs subset characterised by high expression of CXCL14 that predominantly existed in the advanced LUAD tissue and promotes tumour invasion and metastasis through enhancing epithelial–mesenchymal transition (EMT) and angiogenesis." (PMID 40162549, 2025). "Finally, we demonstrated that elevate Cxcl14 in fibroblasts could mimic CXCL14+ myCAFs, which promoted the formation of EMT tumour cells, tube‐forming of vascular endothelial cells using functional assay." (PMID 40162549, 2025). "Furthermore, IHC findings suggest that CXCL14 downregulation in ER-, PR-, human epidermal growth HER2+, TNBC, and basal-like subtypes may lead to immune evasion, reduced tumor immunogenicity, and increased aggressiveness." (PMID 40565366, 2025). "Regarding the protein content of these vesicles, αvβ6 integrin and chemokine (C-X-C motif) ligand 14 (CXCL14), highly expressed in metastatic PCa, have been shown to be transferred to monocytes and to confer them M2-like properties, thus contributing to tumor progression." (PMID 39316264, 2024). "Thus, we hypothesize that combinations of CXCL14 with the HPV vaccines will further augment antitumor responses by enhancing T-cell infiltration and MHC-I antigen presentation, leading to robust tumor suppression." (PMID 38400076, 2024). "Interestingly, experiments conducted on animal models with head/neck and cervical cancers revealed that restoring CXCL14 expression in HPV-positive cancer cells showed an evident increase in NK and T cells in the tumor-draining lymph nodes, contributing to strong anti-tumor responses in vivo." (PMID 38732382, 2024). "Furthermore, upregulated CXCL14/17 expression showed negative correlation with the abundance of three tumor-infiltrating lymphocytes (CXCL14: Tcm CD8, Act CD4, CD56dim; CXCL17: Tcm CD8, Act CD4, Tem CD4)." (PMID 38232115, 2024). "In addition, with the prolonged treatment of HepG2 cells with 20 μg/mL of the CXCL14 protein, the expression levels of pro-apoptotic genes BAK and BAX increased significantly, while the expression levels of tumor pro-proliferation genes HIF1A, mTOR and CDK1 decreased significantly." (PMID 37835641, 2023). "At the same time, GO enrichment analysis shows that process such as amino acid transport, RNA polymerase 1 complex, and activity were only enriched in the CXCL14+ tumor cell subgroup and not in other tumor subgroups, suggesting that this subgroup is actively proliferating." (PMID 37858183, 2023). "However, four tumor markers (POSTN, pSMAD2/3, CXCL14, ADH1B, FAP) that have previously been reported to predict suboptimal debulking were selected in our model, although only p-SMAD2/3 was in the same direction but with lower discriminatory performance compared to prior reports." (PMID 36761962, 2023). "In addition, we have proved, that simultaneous CXCL14 and CRP determinations might be more useful in CRC diagnosis than commonly used tumor marker – CEA, and CRP combination." (PMID 37848726, 2023). "Notably, besides its inflammatory role, CXCL14 in the TME may directly stimulate malignant cells and contribute to EMT and tumor metastasis." (PMID 35439170, 2022). "Oncogenic role of ROS is with no doubt, while CXCL14 may have tumor-suppressive or tumor-supportive functions, depending on the type of the tumor." (PMID 34744744, 2021). "CAFs directly stimulate cancer cell growth and also enhance tumor angiogenesis by paracrine signaling, such as vascular endothelial growth factor (VEGF), hepatocyte growth factor (HGF), growth differentiation factor 15 (GDF15), C-X-C Motif Chemokine Ligand 12 (CXCL12) and CXCL14." (PMID 34681633, 2021). "Some CAF-derived factors such as the chemokine CXCL14 exert autocrine effects on fibroblasts, while other CAF-derived factors act in a paracrine manner stimulating cancer and stromal cells (e.g., endothelial cells, immune cells), and are involved in the recruitment of host cells into the tumor." (PMID 24734219, 2014).
tumor (continued). "In order to investigate whether CXCL14/BRAK suppresses the growth of tumor cells of other tissue origins in a paracrine or endocrine fashion, we produced CXCL14/BRAK transgenic (Tg) mice and examined the growth of tumor cell transplants in them." (PMID 23762619, 2012). "Besides, flow cytometry analysis revealed that Cxcl14‐OE cells promoted the higher proportions of tumour cells in the S phase while could not significantly affect the apoptosis process." (PMID 40162549, 2025). "Thus, the local administration of CXCL14 directly into the TME could be an alternative approach to induce adaptive antitumor immune responses in combination with other immune-modulating therapies (e.g., a tumor vaccine)." (PMID 38400076, 2024). "One possible explanation of this apparent discrepancy between CXCL14 expression and tumor growth is that although the expression of CXCL14 is stimulated in tumor cells, its tumor inhibitory activity may not be sufficient to suppress tumor growth." (PMID 31014014, 2019). "Although the receptor for CXCL14 is still unknown, it has been reported that CXCL14 is able to synergize with CXCL12 via allosteric modulation of CXCR4, and recruit myeloid DCs to the tumor sites, where it likely promotes their maturation to sustain antitumor immunity." (PMID 30591657, 2018). "Thus CXCL14/BRAK may be a very promising molecular target for tumor suppression without side effects." (PMID 23762619, 2012). "Again, while this is a PNET tumor model, and not PDAC, it is interesting to highlight how intra-tumoral myeloid cells can induce the expression of CXCL14 in a beneficial manner, due to its angio-static properties." (PMID 38339310, 2024). "On the contrary, CXCL4, CXCL9, CXCL10, CXCL11, CXCL12, CXCL13, and CXCL14, lacking the ELR amino acid motif (ELR−), can inhibit tumor angiogenesis." (PMID 34497764, 2021). "Transgenic mice expressing 10-fold more CXCL14 protein than wild-type C57BL/6 mice showed reduced rates of chemical carcinogenesis, transplanted tumor growth, and metastasis without apparent side effects." (PMID 31014014, 2019). "CXCL14 overexpression did not change tumor weight in nude mice, while it decreased tumor weight in wild-type BALB/c mice, resulting in an increased tumor weight in nude mice compared with WT Balb/c mice." (PMID 36012586, 2022). "We previously reported that the chemokine CXCL14 exhibits tumour-suppressive effects against xenografted HNSCC cells, which may be classified into two groups, CXCL14-expressing and non-expressing cells under serum-starved culture conditions." (PMID 27399917, 2016).
cancer (112 papers, 2009 to 2026). A tumor composed of atypical neoplastic, often pleomorphic cells that invade other tissues. "By analyzing multiple scRNA‐seq and spatial transcriptomic datasets, we identified a unique subset of CXCL14+ myofibroblastic CAFs (myCAFs), emerging during the early differentiation phase of pan‐cancer invasiveness‐associated THBS2+ POSTN+ COL11A1+ myCAFs." (PMID 40162549, 2025). "We found that cancer cells cocultured with CAFs deficient in CXCL14 expression presented increased sensitivity to cisplatin." (PMID 40898244, 2025). "When we further stratified patients into early-stage and late-stage cancer groups for additional analysis, we observed that high CXCL14 IHC score in CAFs was particularly associated with a favorable prognosis in advanced stages." (PMID 40759242, 2025). "This possibility is further supported by the association of high CXCL14 expression with better patient survival in multiple cancers, including HNSCC and CxCa." (PMID 38400076, 2024). "CXCL14, a homeostatic chemokine in squamous epithelia, is known for its association with cancer as being abundantly expressed in normal tissue but significantly downregulated in some tumors." (PMID 38400076, 2024). "ADAMDEC1 + /CCL8 + and CXCL14 + fibroblasts were preferentially co-localized with the IgG + plasma cells, in accordance with the observed presence of CXCL14 + cancer-associated fibroblast and ADAMDEC1 + /CCL8 + fibroblast in MMRp CRC." (PMID 38110959, 2023). "CXCL14+ cancer-associated fibroblasts (CAFs) and CCL8 fibroblast-like cell proportions were also higher in AC and MC tissues than in normal tissue." (PMID 37091868, 2023). "Chemokine ligand 14 (CXCL14) has been reported to be associated with different cancer cell migration and invasion." (PMID 37056937, 2023). "CXCL14+ cancer-associated fibroblasts and CCL8 fibroblast-like cell proportions were higher in both AC and MC tissues than in normal colon tissue." (PMID 37091868, 2023). "The possible explanation for such conflicting role of CXCL14 in cancer is associated with the origin of CXCL14: epithelial-derived CXCL14 is an antitumor factor, whereas fibroblast-derived CXCL14 is an oncogenic regulator." (PMID 35669852, 2022). "LINC00092 expression is modulated in the response to CXCL14, a chemokine secreted by cancer-associated fibroblasts (CAFs) linked to metastasis." (PMID 31191327, 2019). "Downregulation of CXCL14 associated with carcinoma progression was later reported for various other types of carcinomas, including adenocarcinomas and squamous cell carcinomas." (PMID 31014014, 2019). "Pathway enrichment analysis was most significant for evidence of epithelial-mesenchymal transition (EMT) in the C1 tumors, with concordant loss of E-cadherin (CDH1) and upregulation of CXCL14, both prognostic biomarkers in diverse other cancers 23–25." (PMID 30202034, 2018). "Cxcl14 has been previously implicated in promoting proliferation, particularly in cancer cells, though this is the first report of a role for Cxcl14 in muscle development." (PMID 28775895, 2017). "Here we show that, while expression of many proinflammatory chemokines is increased, CXCL14 expression is significantly decreased in HPV-associated cancer progression." (PMID 27143385, 2016). "Given the well-known essential role of exosomes in intercellular communication and cancer progression, we thus hypothesized that exosomes might be an underlying mechanism about the role of CXCL14 in M2 macrophage polarization." (PMID 35669852, 2022). "Downregulation of CXCL14 has also been observed in HPV-associated cancers." (PMID 31428574, 2019). "However CXCL14 has been identified in cancer associated stromal fibroblasts as a promoter of migration and ERK-dependent proliferation." (PMID 29507348, 2018). "CXCL14 expression is downregulated in HPV-associated cancer progression." (PMID 27143385, 2016).